IL1B (interleukin 1 beta)
Diseases named in the same sentence as IL1B in open-access papers (continued):
Sharing a sentence is not in itself a finding about the gene and the disease.
tumor (continued). "We next hypothesised that CAF-derived IL-1β may affect the recruitment of myeloid cells into the tumour microenvironment via activation of NF-κB-related signalling, as previously shown." (PMID 31558756, 2019). "Therefore, the results further provide a beneficial strategy for preventing tumor metastasis by regulating NLRP3 inflammasome in immune cells and thereby reducing IL-1β levels in tumor sites." (PMID 31439870, 2019). "Similarly, treatment with IL-1β of vascular smooth muscle cells (VSMC) from small tumor vessels, also resulted in improved VEGF transcription and stability in a p38 MAPK dependent manner." (PMID 31293586, 2019). "The supernatants of tumor cells induced the secretion of high levels of IL-1β by THP1 cells." (PMID 30760333, 2019). "As could be predicted based on its ability to enhance angiogenesis, IL-1β has also been shown, in multiple models across multiple cancer types, to enhance tumor cell metastasis." (PMID 31231372, 2019). "Furthermore, reductions in open field locomotion in all mice exposed to a tumor (combined tumor-bearing and -resected groups) were predicted by elevated brain Il1α and Il1β gene expression (p < 0.05 in both cases)." (PMID 31019214, 2019). "Moreover, the genotypes of rs1143623, rs16944, and rs10490571 were significantly correlated with serum IL‐1β levels and other tumor markers." (PMID 31297985, 2019). "Furthermore, inflammation induces the accumulation of immune cells such as “antitumor” M1 macrophages (producing ROSs, IL-1β, TNFα, IL-6, and IL-12) in the tumor microenvironment, which are then reprogrammed by the tumor cells to a M2 phenotype." (PMID 31662751, 2019). "Indeed, tumor-specific Th9IL-4+IL-1β cells displayed significantly higher tumor-specific killing activity compared to classic Th9IL-4+TGF-β and Th2 cells in the in vitro cytolytic killing assay." (PMID 30914642, 2019). "In addition, the secretion of IL1β and matrix metalloproteinases from neutrophils enhances the extravasation of tumor cells." (PMID 30944838, 2019). "For instance, PGE2 increase Th17 through the production of IL-23 and IL-1β by DCs and macrophages, while it can also induce expansion of IL-10 producing Treg type-1 cells (Tr1) as a result of tumor cells secretion as well as expression of COX2/PGE2 by Treg cells." (PMID 31024835, 2019). "Immunofluorescence staining was performed to identify IL-1β secreting cells in the tumor stroma." (PMID 30760333, 2019). "Moreover, IL-1β and IL-6 are also elevated in the tumor-adipocyte microenvironment and interact with adipocytokines to aggravate tumor metastasis." (PMID 31500658, 2019). "Analysis of immune cell infiltration in tumours injected with WT vs. inflammasome-deficient fibroblasts indicated that attenuated tumour growth and metastasis in mice in which NLRP3/IL-1β were knocked down, was associated with reduced recruitment of CD11b+Gr1+ myeloid cells." (PMID 31558756, 2019). "Moreover, CAF-derived IL-1β also upregulated the expression of metalloproteases in tumour cells, potentially enhancing their invasiveness." (PMID 31558756, 2019). "Next, we investigated whether tumor-specific Th9IL-4+IL-1β cells possess antitumor capacity in vivo." (PMID 30914642, 2019). "Furthermore, this approach also increased cytokine production in the tumor region, including that of IL-1β, TNF-α, IFN-γ, and GM-CSF49." (PMID 31827064, 2019). "Cytokine profiling of patients with NSCLC has shown increased levels of IL-1β in tumor specimens." (PMID 32039025, 2019). "We therefore hypothesised that IL-1β secretion from activated mammary CAFs upregulated the expression of adhesion molecules on tumour ECs in vivo, and thus facilitated cancer cell migration across the blood vessel endothelium." (PMID 31558756, 2019). "Thus, the physiological pro-inflammatory functions of IL-1β are activated in breast CAFs and facilitate tumour metastasis." (PMID 31558756, 2019).
tumor (continued). "Dual blockade of IL-2 and IL-15 abrogated the IL-1β enhancement of ACT-mediated tumor regression." (PMID 31405895, 2019). "However, our study and previous studies have shown that irradiating microglial cells increases expression of both Il1b and Tnfa, both of which contribute to a localised inflammatory response to foreign or tumour antigens." (PMID 30722781, 2019). "As a molecule downstream of the inflammasome, IL-1β has been demonstrated to promote tumor progression by recruiting myeloid-derived suppressor cells, which might inhibit the antitumor immune response." (PMID 31242947, 2019). "IL-1β promotes the recruitment of tumor-promoting myeloid cells in tumors." (PMID 31557902, 2019). "Moreover, IL-1β-producing macrophages and IL-17-producing γδ T cells secrete G-CSF to promote neutrophil development in the tumor." (PMID 31474975, 2019). "We performed multiplex immuno-assay (Luminex) to assess the presence of inflammatory cytokines involved in the regulation NK cells function, such as TNF-α, IFN-γ, IL-6, IL-15, and IL-1β, in the tumor microenvironment (black bars) and in the healthy adjacent tissue microenvironment (white bars)." (PMID 31105699, 2019). "It therefore appears that increased IL-1B, observed in bone metastasis, may stimulate the niche leading to outgrowth tumour cells disseminated in this site." (PMID 31783893, 2019). "However, this method is typified by tumor recurrence after treatment, which is related with decreased IL-1β levels." (PMID 31754923, 2019). "Furthermore, the expressions of MMP-2 and VEGF involved in metastasis, as well as inflammatory genes IL-1β, IL-6 and IL-10, showed dose-dependent decrease in tumor tissue after cisplatin exposure." (PMID 32257905, 2019). "Inhibition of IL-1β activity prevents tumor invasiveness and metastatic colonization." (PMID 30683126, 2019). "IL-1β then attracts IFN-γ secreting CTLs to the tumor site via IL-17-producing γδ T-cells." (PMID 31379850, 2019). "Moreover, we identified that tumor cells communicate with astrocytes, where tumor cell-derived interleukin-1 beta (IL-1β) and tumor necrosis factor alpha (TNF-α) increased the expression of TGF-β2 in astrocytes." (PMID 31602400, 2019). "Moreover, in Ak4.4, Pan02, KPC, and iKRAS pancreatic adenocarcinoma, adipocytes of obese population secrete increased levels of IL-1β to recruit neutrophils to the tumor along with enhancing Treg infiltration, and hindrance of CD8+ T cell infiltration." (PMID 31474975, 2019). "Thus, Tmem176b deletion enhances CTL-mediated tumor control through mechanisms involving the caspase-1/IL-1β pathway." (PMID 31085177, 2019). "Immature MDSCs are generated from BM cells and then they expand and migrate to the TME where a complex milieu of tumor- or stromal-derived factors including vascular endothelial growth factor, IL-6, IL-1β, GM-CSF, transforming growth factor β as well as PGE2 modulate their suppressive function." (PMID 31920649, 2019). "However, other studies found that low IL-1β concentrations promote CD4+ T cells to secrete IL-17, inhibiting the body’s anti-tumor effects, while high IL-1β concentrations activate CD8+ T cells and promote anti-tumor effects." (PMID 31754923, 2019). "IL-1β is known to promote tumor proliferation, angiogenesis, metastasis, in a number of cancers." (PMID 31374832, 2019). "Tumor markers and IL‐1β levels were measured by electrochemiluminescence and ELISA, respectively." (PMID 31297985, 2019). "Similarly, amplification of mTOR in liver cancer leads to increased levels of IL-1β, which activates NF-kB, thereby driving tumor suppressive SASP and immune cell recruitment." (PMID 31611871, 2019). "The chitinase family could induce the generation of pro- and anti-inflammatory cytokines and chemokines, such as interleukin (IL)-1β, IL-6, IL-12, and IL-13, making them potential modulators in an inflammatory tumor microenvironment." (PMID 31238895, 2019). "b Tumor cells release ASC that activates TAMs to secrete IL-1β (c)." (PMID 30760333, 2019).
tumor (continued). "Afterwards, the expression levels of 12 cytokines including IL-1a, IL-1b, IL-2, IL-4, IL-6, IL-8, IL-10, IL-12, IL-17A, TNFα, IFNγ and GM-CSF in secretome of hWJ-MSCs alone as well as in supernatant of tumor cells before and after treatment with hWJ-MSCs secretome were evaluated." (PMID 31857970, 2019). "Interestingly, a recent study suggests that tumour-derived Wnt promotes IL1β secretion by macrophages, suggesting the possibility of a feed-forward signalling mechanism promoting metastasis." (PMID 31676788, 2019). "Strikingly, while control mammary fibroblasts augmented tumour growth, genetic depletion of Nlrp3 or Il1b in injected fibroblasts significantly attenuated tumour growth and weight, suggesting that CAF-derived inflammasome is functionally important for tumour growth in vivo." (PMID 31558756, 2019). "IL-1β increased tumor progression in mouse tumors, using IL-1β or IL-1R1 gene targeted mice." (PMID 31557902, 2019). "Subsequently, we examined whether these anti-tumor drugs could mediate the activation of inflammasome signaling, as measured by IL-1β secretion." (PMID 31156650, 2019). "Indeed, in preliminary immunohistochemical studies on a small number of human HPV‐negative and HPV‐positive OPC biopsies, we found, in general, that HPV‐negative tumour cells appeared to express more abundant levels of IL‐1β than HPV‐positive tumour cells." (PMID 30191960, 2019). "The demonstration of a potent pro-tumour effect of IL-1β in PDAC allowed us to hypothesise that interference with IL-1 receptor signalling in cancer cells by suppressing COX-2 could be a promising method to sensitise PDAC cells to gemcitabine." (PMID 31588122, 2019). "In CRCSC-dominant primary tumors, CRCSC exosome secretion is increased, and the exosomes are transported to the bone marrow, where they extend neutrophil survival via exosomal tri-phosphate RNAs to activate PRR-NF-κB signaling and IL-1β expression (distal effect, the first tumor-host interaction)." (PMID 30683126, 2019). "Moreover, analysis of lungs revealed a significant decrease in metastatic lesions in mice injected with Il1b−/− fibroblasts, suggesting that CAFs at the primary tumour affect the formation of distant metastases." (PMID 31558756, 2019). "However, the origin of IL-1β is confusing because the tumour microenvironment is typically anti-inflammatory and immunosuppressive." (PMID 31588122, 2019). "To further analyse whether CAR-147 macrophage reinfusion causes cytokine storms like CAR-T cell infusion does, we detected the cytokines IL-1β, IL-6, IL-12, TNFα, and IFNγ in serum samples and tumour homogenates." (PMID 31570753, 2019). "Tumor-secreted factors such as GM-CSF, IL-1β, IL-6, TGF-β, and TNF mediate expansion of MDSCs." (PMID 32039025, 2019). "Therefore, further experiments are warranted to characterize IL-1β-expressing macrophages in tumor tissues." (PMID 31705021, 2019). "As a tumor is often described as being like a “chronic wound”, the hypoxic conditions and high concentration of cytokines and growth factors IL-1α, IL-1β, IL-6, FGF-2, IGF-1, TGF-β, VEGF-A, HIF-1α, EGF, TGF-α are a likely trigger for MSCs recruitment to tumor microenvironments." (PMID 31569731, 2019). "In summary, we identified tumor-derived IL-1α and IL-1β as key cytokines in driving TSLP secretion by CAFs and tumor-released ASC, whose expression in PDAC correlates with reduced patients’ survival, as a relevant component in the inflammatory cascade involving activation of IL-1β secretion by TAMs." (PMID 30760333, 2019). "However, treatment with engineered Salmonella S.t-ΔpGlux/pT-ClyA consistently inhibited tumor growth, and IL-1β levels remained high." (PMID 31754923, 2019).
tumor (continued). "Which is the mechanism of ASC release from PDAC cells and whether ASC in tumor cell supernatants is sufficient per se to activate both pro-IL-1β production and processing will need further investigation." (PMID 30760333, 2019). "Furthermore, CCL12 promotes M-MDSCs to migrate to premetastatic lungs in melanoma cell-bearing mice and increases IL-1β and E-selectin expression before the arrival of tumor cells, which is beneficial for tumor cell arrest of endothelial cells." (PMID 30792719, 2019). "However, staining was variable amongst sections and the presence of IL‐1β was observed in tumour sections from certain HPV‐positive biopsies." (PMID 30191960, 2019). "However, a recently published paper has shown that inhibiting IL1β in mouse models enhances tumour cell immunity by synergising with anti-PD-140, which is very promising for future combination therapies." (PMID 31676788, 2019). "IHC staining of mouse tumor tissues demonstrated decreased IL‐1β expression in the shYAP1 group." (PMID 31145543, 2019). "We showed that both chemokines (CXCL12, IP-10, and CCL27) and cytokines profiles (IL-1β and IL-6) were altered in the tumor microenvironment and might reduce NK cell function and recruitment to the tumor site." (PMID 31105699, 2019). "Our findings suggest a fibroblast-driven mechanism wherby IL-1β secreted from mammary fibroblasts, affects the expression of adhesion molecules on ECs at the primary tumour site, as well as in the lungs, thus facilitating the extravasation of tumour cells." (PMID 31558756, 2019). "Therefore, IL-1B is a major candidate in driving the production of chemokines in the tumour microenvironment, which, in turn, sustain tumour development." (PMID 29760166, 2018). "The major products of inflammasome activation, IL-1β and IL-18, are pro-tumorigenic and shown to play an important role in tumor-mediated angiogenesis, hence blocking their function may suppress tumor progression." (PMID 29558453, 2018). "Finally, the release of IL-1β by DC is critical for eliciting tumor-specific IL-17-producing γδ T cells and IFN-γ-producing CTL." (PMID 29462947, 2018). "In recent studies, positive effects of IL-1β produced by macrophages on tumorigenesis and angiogenesis have been reported, but the mechanism of IL-1β production is unknown in the tumor microenvironment." (PMID 30586442, 2018). "Moreover, the secretion of interleukin (IL)-1β (IL-1β) by immune cells in early neoplasia has emerged as an initiator of nuclear factor-κB signaling in fibroblasts involved in their education and production of pro-tumorogenic and pro-inflammatory factors." (PMID 29545811, 2018). "Additionally, the role of IL-1β in angiogenesis, tumor promotion, metastasis, resistance to chemotherapy, and immunosuppression are well-described." (PMID 30631327, 2018). "Through the regulation of IL-1β, Notch may shape the immune infiltrate at the tumor site, affecting both the innate and the adaptive antitumor immune response." (PMID 30154786, 2018). "However, recent studies have reported that IL-1β in tumor tissues is involved in tumor development and progression." (PMID 30586442, 2018). "Importantly, IL-1β-mediated NF-κB induction in KRAS-mutant tumor cells, as well as their resulting MPE-competence, can only be blocked by co-inhibition of both KRAS and IKKα, a strategy that overcomes drug resistance to individual treatments." (PMID 29445180, 2018). "Hence we show that mutant KRAS facilitates IKKα-mediated responsiveness of tumor cells to host IL-1β, thereby establishing a host-to-tumor signaling circuit that culminates in inflammatory MPE development and drug resistance." (PMID 29445180, 2018). "The expression levels of these cytokines were assessed in 4T1 tumours, which revealed a striking similarity to the reparative tissue response, including significantly higher Spp1, Il1b, Csf3, Il6 and Osm expression in 4T1 tumours compared to healthy mammary fat pad tissue." (PMID 30054470, 2018).
tumor (continued). "The increased tumor number was associated with a colonic upregulation of inflammatory mediators (including Il-1β, Il-6, Tnf, G-csf, Mcp1, and Mip1α, but not Il-18) and an early hyperactivation of mTOR pathway." (PMID 29868004, 2018). "Therefore, the mechanism of IL-1β production in macrophages in the tumor microenvironment was investigated in this study." (PMID 30586442, 2018). "Therefore, numerous studies on IL-1β and its inhibition in animal and human tumor models were conducted." (PMID 30042333, 2018). "Cancer-associated adipocytes have been associated with enhanced production of matrix metalloproteinase-11 (MMP-11) and pro-inflammatory cytokines (IL-1β and IL-6), as well as increased degradation of lipids, to provide additional energy to malignant cells at the tumour front." (PMID 30261606, 2018). "The ability of WRE to increase pro-inflammatory cytokines such as IL-1β in PBMC’s may aid in cancerous cell elimination through increased host anti-tumour activity." (PMID 29631586, 2018). "IL-1β promotes tumor development as well by influencing angiogenesis." (PMID 30042333, 2018). "Chronic high-level expression of bioactive IL-1β is an important promotor of tumor development." (PMID 30042333, 2018). "Further experiments are required to test whether IL-1β precursor can have a still unknown function in tumor cells and especially in CSCs." (PMID 30218041, 2018). "Moreover, GSEA highlighted a significant enrichment of the IL1B response signature in ACP tumours using three independent datasets of genes up-regulated upon IL1B treatment (NES = 1.79, 2.25, 2.66, respectively; FDRs < 0.001)." (PMID 29541918, 2018). "Therefore, treatments using “add-on” drugs such as the IL-1β blocker to conventional chemotherapy should be investigated in appropriate tumor models monitoring both the primary tumor and the induction of metastases." (PMID 30042333, 2018). "Altogether, our study shows that BRAFV600E inhibitors upregulate IL-1β release by mouse and human DC which may affect the DC-mediated course of anti-tumor immune responses." (PMID 29983861, 2018). "Furthermore, transcriptional reprogramming of tumor-infiltrating myeloid cells was mediated in part by IL-1β induced NF-kB activation." (PMID 29983861, 2018). "Therefore, IL-1β has been attributed a largely beneficial role in resolving acute inflammations, and by initiating adaptive anti-tumor responses." (PMID 30042333, 2018). "Additionally, chemotherapy triggers cathepsin B release in myeloid-derived suppressor cells, activating the NLRP3 inflammasome leading to MDSC-derived IL-1β and angiogenesis and promoting tumor growth and metastasis." (PMID 30631327, 2018). "While a variable capacity to secrete IL-6, IL-1β and TNF-α is shared by differentially polarized macrophages, an IL-12 low/IL-10 high phenotype is the hallmark of M2 macrophages, which are known to promote tumor growth." (PMID 29454317, 2018). "Importantly, a report in tumor-bearing mice, has suggested that AMs can produce higher levels of IL-1β, after LPS/ATP stimulation." (PMID 30365491, 2018). "The observation that chemotherapeutics may increase IL-1β levels in tumor patients may be detrimental for tumor therapy and therefore needs to be taken into consideration." (PMID 30042333, 2018). "Recent evidence indicates that targeting IL-1B signalling may provide promising new treatments that can hold tumour cells in a dormant state within bone thus preventing formation of overt bone metastases." (PMID 29760166, 2018). "Analysis of the microarray data for the FAP+ TAM population isolated from 4T1 tumours revealed that these cells were also directly expressing some of the acute wound inflammatory response genes, including Il1b, Il6 and Osm, alongside the phenotypic markers Hmox1 and Fap." (PMID 30054470, 2018).